IGHV5-10-1 (immunoglobulin heavy variable 5-10-1)
Description:
V region of the variable domain of immunoglobulin heavy chains that participates in the antigen recognition. Immunoglobulins, also known as antibodies, are membrane-bound or secreted glycoproteins produced by B lymphocytes. In the recognition phase of humoral immunity, the membrane-bound immunoglobulins serve as receptors which, upon binding of a specific antigen, trigger the clonal expansion and differentiation of B lymphocytes into immunoglobulins-secreting plasma cells. Secreted immunoglobulins mediate the effector phase of humoral immunity, which results in the elimination of bound antigens. The antigen binding site is formed by the variable domain of one heavy chain, together with that of its associated light chain. Thus, each immunoglobulin has two antigen binding sites with remarkable affinity for a particular antigen. The variable domains are assembled by a process called V-(D)-J rearrangement and can then be subjected to somatic hypermutations which, after exposure to antigen and selection, allow affinity maturation for a particular antigen.
Synonyms: IGHV5-a
Gene: Immunoglobulin variable (V) gene on chromosome 14 (106,107,972 to 106,108,464, reverse strand). Ensembl gene ENSG00000282651.
Subcellular location: Secreted; Cell membrane
Gene Ontology:
Molecular function: antigen binding
Biological process: immunoglobulin mediated immune response
Cellular component: extracellular region; plasma membrane
Homologues: Orthologues: tropical clawed frog XB5734592 (52% identical). Paralogues in human: IGHV5-51 (93% identical), IGHV1-69 (61% identical), IGHV1-69-2 (60% identical), IGHV1-69D (60% identical), IGHV1-46 (59% identical), IGHV1-18 (58% identical), IGHV1-2 (58% identical), IGHV1-3 (58% identical), IGHV1OR15-1 (58% identical), IGHV1OR15-9 (57% identical), IGHV1-24 (56% identical), IGHV1-45 (55% identical), and 65 more.